KRT14 (keratin 14)
Description:
Structural component of intermediate filaments in basal keratinocytes of stratified epithelia. Forms obligate heteropolymers with the type II keratin KRT5, contributing to the keratin intermediate filament network that confers mechanical strength and structural integrity to the basal layer of the epidermis and other stratified epithelial. The nonhelical tail domain is involved in promoting KRT5-KRT14 filaments to self-organize into large bundles and enhances the mechanical properties involved in resilience of keratin intermediate filaments in vitro.
Synonyms: K14; CK14; EBS1; EBS1A; EBS1B; EBS1C; EBS1D; EBS3; EBS4; NFJ
Tractability: Antibody: its Gene Ontology location is reachable by antibodies, with medium confidence. PROTAC: UniProt records ubiquitination sites on it; ubiquitination databases record sites on it.
Gene: Protein-coding gene on chromosome 17 (41,582,279 to 41,586,895, reverse strand). Ensembl gene ENSG00000186847.
Subcellular location: Cytoplasm; Nucleus
Subcellular location (Human Protein Atlas): Intermediate filaments
Pathways (Reactome):
Developmental Biology: Developmental Lineage of Mammary Gland Myoepithelial Cells; Differentiation of Keratinocytes in Interfollicular Epidermis in Mammalian Skin; Formation of the cornified envelope; Keratinization
Cell-Cell communication: Type I hemidesmosome assembly
Gene Ontology:
Molecular function: keratin filament binding; protein binding; structural constituent of cytoskeleton; structural constituent of skin epidermis; structural molecule activity
Biological process: hair cycle; intermediate filament bundle assembly; epidermis development; intermediate filament organization; keratinocyte differentiation; morphogenesis of an epithelium; positive regulation of keratinocyte differentiation
Cellular component: cytoplasm; extracellular exosome; intermediate filament; intermediate filament cytoskeleton; keratin filament; nucleus; protein-containing complex; cytoskeleton; cytosol; basal part of cell; cell periphery; cornified envelope
Genetic constraint (gnomAD): Loss-of-function variants: 30 observed, 43.65 expected, observed/expected ratio (o/e) 0.69, 90% interval 0.51 to 0.93. The upper end of that interval is the gene's LOEUF score, 0.93, which puts it in group 3 of 6, group 1 being the genes least tolerant of losing a copy. Missense variants: 535 observed, 623.99 expected, observed/expected ratio (o/e) 0.86, 90% interval 0.8 to 0.92. Synonymous variants: 241 observed, 252.59 expected, observed/expected ratio (o/e) 0.95, 90% interval 0.86 to 1.06.
Homologues: Orthologues: chimpanzee KRT14 (99% identical), mouse Krt14 (91% identical), rat Krt14 (91% identical), guinea pig KRT14 (89% identical), dog KRT14 (73% identical). Paralogues in human: KRT16 (83% identical), KRT17 (72% identical), KRT15 (64% identical), KRT13 (60% identical), KRT10 (59% identical), KRT19 (56% identical), KRT24 (56% identical), KRT12 (54% identical), KRT9 (53% identical), KRT27 (50% identical), KRT36 (50% identical), KRT28 (49% identical), and 56 more.
Diseases named in the same sentence as KRT14 in open-access papers:
KRT14 is named in the same sentence as 233 diseases in open-access papers, as found by Europe PMC text mining. Sharing a sentence is not in itself a finding about the gene and the disease. The quoted sentences say what the papers report.
breast cancer (201 papers, 2006 to 2026). A primary or metastatic malignant neoplasm involving the breast. "Upregulation of KRT14 has been associated with a more invasive breast cancer phenotype, while increased abundance of KRT8 is common in malignant cells." (PMID 38915368, 2024). "Hereditary and sporadic BRCA1-associated breast cancers are often triple-negative and express basal markers, such as keratin 14 (K14) and K5." (PMID 38499540, 2024). "In summary, HR breast epithelia of women harboring cancer-predisposing mutations had significantly higher levels of KRT14 expression in their LEps compared with AR, a property of LEps observed in both women of advanced age and women with breast cancer." (PMID 35187501, 2021). "In breast cancer, plakoglobin and keratin 14 have been reported to be associated with desmosomes and hemidesmosomes and crucial for CTC cluster formation." (PMID 30646614, 2019). "Mammary tumors from mice fed a soy diet more frequently expressed markers associated with metaplastic breast cancer including cytokeratin 5, cytokeratin 14, p63 and the presence of osseous matrix." (PMID 25655427, 2015). "Moreover, KRT14 expression has been implicated in MHC class II presentation in breast cancer, suggesting that down-regulation of KRT14 in TNBC could result in increased MHC II expression and facilitate the activation of CD4+ T cells." (PMID 38566092, 2024). "In human breast cancer patients, expression levels of KRT14 and KRT6A negatively correlated with expression of IGF1R." (PMID 42279332, 2026). "Expression of Pik3ca-mutations in luminal cells (e.g., using promoters MMTV, WAP and Krt8) mostly evoked adenosquamous mammary carcinomas, which exhibited mixed-lineage features highlighted by the presence of KRT14/KRT8 & KRT18 double-positive cancer cells." (PMID 40676433, 2025). "It is noteworthy that BRCA1 and FANCD2 mutation carriers commonly have KRT14-positive breast tumors and among sporadic breast cancer patients those with KRT14-positive tumors have markedly poorer prognosis than the patients with KRT14-negative tumors." (PMID 38597967, 2024). "Compare to KRT14− breast cancer cells, KRT14+ breast cancer cells exhibited more invasiveness in three-dimensional organoid assays and an enhanced ability to develop circulating tumor cell clusters." (PMID 38566092, 2024). "Several breast cancer mouse models have shown that shRNA-mediated KRT14 knockdown or diphtheria toxin-mediated ablation of KRT14+ tumour cells resulted in smaller primary tumours and significantly fewer metastatic lesions." (PMID 39408880, 2024). "In this study, we reveal, for the first time, that FOXO3a directly interacts with the KRT14 promoter, transcriptionally repressing KRT14 expression in breast cancer." (PMID 38566092, 2024). "Conversely, we observed that feeding mice a high-cholesterol diet significantly upregulated KRT14 expression and promoted breast cancer metastasis." (PMID 38566092, 2024). "Early studies established the role of KRT14+ LCs in collective invasion across several breast cancer subtypes." (PMID 39408880, 2024). "Work in our lab and others have found that leader cells are positive for cytokeratin-14 (K14) in collective migration of breast cancer cells." (PMID 38165954, 2024). "On the other hand, collective invasion in breast cancer can be initiated by cancer cells that express basal epithelial markers, with keratin-14 being a notable representative of these markers." (PMID 37975220, 2024). "Consistent with earlier studies, our findings in this study revealed that knocking down KRT14 led to reduced metastasis of 4T1 breast cancer and prolonged survival in mice." (PMID 38566092, 2024). "In many breast cancer models, luminal cells that express basal cell markers (basal-like cells) including cytokeratin 14 (K14) become the leaders of invasion." (PMID 38849373, 2024).
breast cancer (continued). "In mouse mammary cancer models KRT14 is needed for both invasion and distant metastasis and KRT14 overexpression is also associated with an increased invasive potential of human epithelial carcinomas, such as breast and ovarian malignancies." (PMID 38597967, 2024). "Transcriptomic profiling of KRT14+ LCs in breast cancer demonstrates that major histocompatibility complex (MHC) class-II genes are downregulated in LCs." (PMID 39408880, 2024). "Breast cancer cells can propagate KRT14-positive (KRT14+) and KRT14-negative (KRT14−) daughter cells via the asymmetric division and thereby generate heterogeneity." (PMID 38566092, 2024). "A previous study showed that KRT14+ breast cancer cells located at the invasion front or interface between the tumoroid and extracellular collagen and mediated collective dissemination." (PMID 38566092, 2024). "KRT14 expression in breast cancer LCs is also negatively correlated with cell surface MHC class-I expression, indicating that LCs directly engage in immune evasion strategies to increase their chances of successful colonisation." (PMID 39408880, 2024). "Ex vivo breast cancer and salivary adenoid cystic carcinoma 3D culture assays demonstrated that KRT14 knockdown abrogated the appearance of multicellular invasive strands." (PMID 39408880, 2024). "The formation of CTC clusters is highly dependent on the expression of the basal cell marker, KRT14, in ovarian and breast cancer." (PMID 37240349, 2023). "Invasive leader cells are molecularly and behaviorally distinct from bulk tumor cells, and in some mammary tumor models and human breast tumors express the basal epithelial marker cytokeratin 14 (K14)." (PMID 37147680, 2023). "To investigate potential epigenetic regulation of KRT5/6A/6B and KRT14/16/17, we first compared their regional epigenetic landscapes on chromosome 12 and 17, respectively, in luminal and basal breast cancer cell lines and tumors." (PMID 35440136, 2022). "Our breast cancer data mining in the PAM50 subtypes of breast cancer cohort display a positive correlation between EZH2 and KRT14 expression selectively in basal breast cancer subtype (TNBC) among all breast cancer subtypes." (PMID 36446780, 2022). "High levels of KRT14 have been found in basal-like breast cancer as well as in the basal layer of the stratified squamous epithelium." (PMID 36293530, 2022). "KRT14 was positive in leader tumor cell clusters which disseminate collectively in breast cancer metastasis." (PMID 35078507, 2022). "Both KRT14 and Twist expression have also been identified as drivers of collective invasion and markers of breast cancer micro-metastases." (PMID 34470672, 2021). "For example, overexpression of STX2 can facilitate the carcinogenesis of mice breast cancer by increasing C/EBPβ, keratin-14, matrix metalloproteinase-3 (MMP-3), and β-catenin expression." (PMID 33754003, 2021). "KRT14-expressing breast cancer cells were shown to lead the collective invasion process and to activate a basal gene program, which included TP63 and KRT5, needed for the initial phases of metastasis in breast cancer cells." (PMID 35187501, 2021). "In this GEMM, the cytokeratin 14 (K14) promoter sequence was used to drive the expression of Cre recombinase, which meant that mice not only developed mammary tumors but also skin tumors." (PMID 34771558, 2021). "Recent breast cancer studies clearly demonstrated that the KRT14-expressing sub-population of cells regulated the formation of polyclonal tumour deposits both in vitro and in vivo." (PMID 31443478, 2019).
breast cancer (continued). "In breast cancer, leader cells co-express multiple basal epithelial markers such as KRT14, KRT5, P63, and P-cadherin, in conjunction with markers of the luminal epithelium including KRT8, KRT18, and E-cadherin, marking them as a progenitor-like population." (PMID 30909510, 2019). "We previously found that Zfp217 overexpression promotes an increase in a progenitor cell population that expresses markers of luminal (keratin 8, K8) and myoepithelial (keratin 14, K14) cells (K8+K14+) during breast cancer progression." (PMID 29312549, 2017). "MDA-MB-231 human breast cancer cells have previously been found to express mixed staining patterns of human keratin 18 (luminal cell marker) and human keratin 14 (myoepithelial cell marker)." (PMID 23155468, 2012). "This suggests that KRT14 is an absolute determinant of bisphenol-induced breast cancer development." (PMID 41301867, 2025). "Furthermore, the proportion of KRT14+ LCs is significantly enriched in breast cancer micro-metastatic tumours compared to relatively low numbers observed in the primary tumour and established secondary metastases (43–67% vs. 0.9% and 2.5%, respectively)." (PMID 39408880, 2024). "Finally, we analyzed expression levels of KRT14 and FOXO3a in 100 tumor tissues from patients with biopsy-proven breast cancer using immunohistochemistry." (PMID 38566092, 2024). "KRT14 is a structural component of the cytoskeleton and is known to be positively expressed in the leader tumor cell clusters that collectively disseminate in breast cancer metastasis." (PMID 38566092, 2024). "Since KRT14 is downstream of cholesterol, it can be regulated by modulating upstream cholesterol metabolism, thereby influencing the metastatic characteristics of breast cancer." (PMID 38566092, 2024). "In breast cancer, KRT14+ epithelial tumor cell clusters promoted to distant organs metastases." (PMID 37169018, 2023). "Furthermore, the expression of several cytokeratin genes such as KRT5, KRT6B, KRT14, and KRT17 was associated with basal-like breast cancer, a breast cancer subtype that is highly associated with poor treatment outcome." (PMID 35911770, 2022). "To draw a clinical correlation between EZH2 and KRT14 expression, we mined Breast Cancer Yau (2010) dataset from breast cancer patients and observed a high EZH2 and KRT14 mRNA expression exclusively in the basal (TNBC) subtype compared to the other breast cancer subtypes." (PMID 36446780, 2022). "KRT14 was proved to be a key regulator in metastasis of breast cancer." (PMID 34980950, 2021). "Keratin 14 (KRT14), a member of the keratin type I family is overexpressed in breast cancer." (PMID 33801373, 2021). "Similarly, vitamin D compounds showed an inhibitory effect ontriple negative breast cancer by downregulating key markers of breast cancer stem cells and by upregulating myoepithelial differentiating markers (cytokeratin 14 and smooth muscle actin)." (PMID 29849001, 2018). "While whey acidic protein (WAP)- and β-lactoglobulin-cre-induced Apc deletion increased squamous metaplasias, keratin-14 (K-14)-mediated Apc deletion led to mammary tumor formation, suggesting that the cell type in which APC is inactivated is critical for the associated phenotypes." (PMID 22216254, 2011). "Indeed, changes in keratin expression during breast cancer invasion (that is, from a luminal keratin 8 to a basal keratin 14) (ref.46) could also affect the mechanical properties and responsiveness of the keratin network to external signals." (PMID 37709930, 2023). "Thus, exploring the detail function of KRT14 in breast cancer is required in further studies." (PMID 36998462, 2023). "Interestingly, comparative analysis of the basal‐like vs. luminal breast cancer cell types markers in ABI1 KO mice showed that the genes of basal‐like cells (Krt14, Vim) are responded to Abi1 depletion, however luminal cell type genes markers (Krt8, Krt18, Sox9, Estr1) do not." (PMID 34967509, 2022).
breast cancer (continued). "Similarly, KRT14+ cell “stemness” was demonstrated in vivo using breast cancer mouse models." (PMID 30909510, 2019). "The results revealed elevated levels of several breast cancer-related genes, including AZGP1, GATA-3, KRT14, XIST, and ESR1." (PMID 40474021, 2025). "Particularly, ERK3 knockdown in pancreatic cancer has similar effects to those reported for breast cancer, resulting in reduced protein expression of YAP, KRT14, and SNAIL." (PMID 40936697, 2025). "The gene detection results demonstrated elevated levels of breast cancer-related genes, including AZGP1, GATA-3, KRT14, XIST, and ESR1." (PMID 40474021, 2025). "As anticipated, infection of breast cancer cells with ADV-ApoA1 promoted cholesterol efflux, reduced KRT14 expression, decreased lung metastases in TNBC-bearing mice, and prolonged their survival." (PMID 38566092, 2024). "Intracellular accumulation of NBR1 is also involved in prometastatic differentiation; it induces aggressive basal differentiation through the expression of cytokeratin 14 and TP63 in breast cancer." (PMID 36831154, 2023). "Intracellular accumulation of NBR1 is also involved in prometastatic differentiation that induces aggressive basal differentiation such as cytokeratin 14 and TP63 in breast cancer." (PMID 36831154, 2023). "Complementarily, Brca1F/F Trp53F/F Krt14-Cre mice develop mammary tumors (designated as BRCA1-null tumors) which mimic basal-like breast cancers and were ER-/PR-/HER-." (PMID 32840210, 2020). "Classification of primary breast cancer RNASeq data based on high/low CEBPB/REST/CTCF revealed that, KRT5, KRT14 and KRT17 mRNAs were significantly upregulated in CEBPBhigh and CTCFlow tumors." (PMID 30335837, 2018). "We found that both COX-2 expression and activity concomitantly modulated TGFβ-promoted breast cancer cells stemness and expression of FN1, CDH2 and KRT14." (PMID 28054666, 2017). "Therefore, we evaluated the expression of the established EMP markers in breast cancer—SNAIL and KRT14—together with other key proteins involved in EMT, such as β-catenin, YAP and its downstream effector CYR61, in shERK3 and shWT cells." (PMID 40936697, 2025). "In MMTV-PyMT breast cancer organoids, KRT14 knockout was shown to have no impact on invasion into collagen I substrate, with invasive behaviour linked to the mechanoresponsive activation of yes-associated protein-1 (YAP)." (PMID 39408880, 2024). "Analysis of tumor tissues from breast cancer patients further confirmed the negative correlation between KRT14 and FOXO3a." (PMID 38566092, 2024). "Invasive luminal B breast cancer LCs were reported to express epithelial markers KRT14 and p63 but lacked expression of typical EMT markers TWIST1, Slug, and vimentin." (PMID 39408880, 2024). "KLF5 was coexpressed with basal markers (KRT5, KRT14 and KRT17) in breast cancer tissue." (PMID 36923542, 2023). "Next, we sought to investigate the protein expression correlation between EZH2 and KRT14 in TNBC patient samples from Breast Cancer Gene-Expression Miner v4.8 and discovered the protein expression of EZH2, and KRT14 is positively (p = 0.0018, r = 0.1) correlated with each other." (PMID 36446780, 2022).